EEF1GP4 (eukaryotic translation elongation factor 1 gamma pseudogene 4)
Gene: Processed pseudogene on chromosome 3 (161,324,913 to 161,326,219, reverse strand). Ensembl gene ENSG00000240138.
Diseases named in the same sentence as EEF1GP4 in open-access papers:
EEF1GP4 is named in the same sentence as 1 disease in open-access papers, as found by Europe PMC text mining. Sharing a sentence is not in itself a finding about the gene and the disease. The quoted sentences say what the papers report.
breast carcinoma (1 paper, 2020). "We find that increased CTSLP8 (Wald p-value = 5.0 × 10− 05), increased EEF1GP4 (Wald p-value = 1.0 × 10− 06), decreased HLA-K (Wald p-value = 8.0 × 10− 05), increased CBX1P3 (Wald p-value = 1.0 × 10− 03), and increased RPS10P20 (Wald p-value = 2.0 × 10− 03) indicate worse prognosis in breast cancer." (PMID 32241256, 2020).